RIPK4 (receptor interacting serine/threonine kinase 4)
Diseases named in the same sentence as RIPK4 in open-access papers (continued):
Sharing a sentence is not in itself a finding about the gene and the disease.
tumor (continued). "Given that Vimentin, MMP2 and Fibronectin are well-known key players of the epithelial-mesenchymal transition (EMT) process in promoting tumor metastasis; our results indicated a pro-metastasis function of RIPK4 by promoting the EMT process in the progression of CSCC." (PMID 26148476, 2015). "In addition to its utility as a diagnostic marker for HSILs, we also revealed that high RIPK4 expression was associated with invasive and metastatic characteristics of CSCC, including advanced FIGO stage, larger tumor size and distant metastasis." (PMID 26148476, 2015). "It is currently not clear whether the oncogenic/tumor suppressing function of RIPK4 is associated with its ability to activate NF-κB." (PMID 37688617, 2023). "Therefore, RIPK4 acts in some cells as a tumor suppressor and in others as a tumor promotor." (PMID 37688617, 2023). "In addition, previous in vivo assays indicated that knockdown of RIPK4 suppressed tumor growth." (PMID 35310605, 2022). "Hence, the context-specific function of RIPK4 in signal transduction mechanisms may depend on the different tumor types." (PMID 35186499, 2022). "The clustering of mutations within the kinase and ankyrin repeat domains strongly indicated non-random mutations and supported the hypothesis that RIPK4 is a putative tumor suppressor for aggressive cSCC." (PMID 32674318, 2020). "Although we did not fully elucidate the mechanism by which RIPK4 promotes tumor metastasis, the observation of a distinct association between RIPK4 and tumor metastasis may have therapeutic and prognostic implications." (PMID 26148476, 2015). "Suppression of RIPK4 expression impairs the survival of DLBCL cells in vitro and inhibits tumor growth of xenografted DLBCL cells in mice." (PMID 35186499, 2022). "Hence, RIPK4 might act as a novel tumor suppressor gene in skin SCC." (PMID 35186499, 2022). "Because RIPK4 can strongly inhibit the migration and invasion of HCC cells over long distances, we next explored the role of RIPK4 in HCC and discussed the signalling pathway that regulates tumour metastasis." (PMID 34222329, 2021). "The prognostic data were combined to analyse the relationship between RIPK4 and HCC patient survival and tumour recurrence." (PMID 34222329, 2021). "In summary, we detected six DEGs (RIPK4, SCNN1A, SLC4A11, ELF3, CLDN4, and SOBP) which can serve as tumor markers for the diagnosis and prognosis of OC." (PMID 33742531, 2021). "The upregulation of RIPK4 promotes activation of the NF-κB signaling pathway, upregulates VEGF, and ultimately promotes tumor cell aggressiveness." (PMID 34124253, 2021). "The most prevalent tumor suppressors identified were ADAM10, AJUBA, receptor interacting serine/threonine kinase 4 (RIPK4), NOTCH2, and NOTCH3, which were all shown to converge on the NOTCH pathway." (PMID 33322834, 2020). "High RIPK4 expression was significantly related to clinical stage (60.7% vs. 46.5% for stage IB2-IIB and IB1; P = 0.048), tumor size (66.7% vs. 47.2% for > 4 cm and ≤4 cm; P = 0.017) and distant metastasis (72.0% vs. 49.7% for + and −; P = 0.037)." (PMID 26148476, 2015). "In contrast, mice overexpressing RIPK4 in the epidermis do not show increased tumor formation when treated with DMBA/PMA, supporting the idea that in keratinocytes RIPK4 acts as a tumor suppressor rather than as a tumor promotor." (PMID 37688617, 2023). "Fifteen additional, potential tumour suppressor genes under the control of Notch or modulating Notch downstream functions have been identified in an animal model of HNSCC, including Adam10, Ripk4, EP300, and Ajuba28, which adds emphasis to the tumour suppressor function of Notch signalling." (PMID 37607974, 2023). "In previous research on RIPK4, we found that RIPK4 affects the occurrence and development of different types of tumours in various ways, and there is a lack of research reports on RIPK4 in HCC." (PMID 34222329, 2021).
tumor (continued). "We found that the expression level of RIPK4 in nontumour tissues was significantly higher than that in tumour tissues, and the level of RIPK4 was significantly positively correlated with postoperative survival and recurrence in HCC patients." (PMID 34222329, 2021). "Whether the absence of RIPK4 or RIPK4 overactivity, depending on the tumor type, affects the response of the cancer cells to cell death-inducing chemotherapeutics has not been investigated." (PMID 37688617, 2023). "It was strongly implied that the mutations were non-random, thus supporting the hypothesis that RIPK4 is a putative tumor suppressor for cSCC." (PMID 32923402, 2020). "Receptor interacting serine/threonine kinase 4 (RIPK4) is a member of the threonine/serine protein kinase family; it plays related functions in a variety of tumours, but its biological function has not been fully revealed." (PMID 34222329, 2021). "However, RIPK4 could not stratify patients in the following clinical stage subgroups: IB2-IIB, no LN metastasis, grade I/II, tumor size (≤4 cm) and tumor size (>4 cm) (P = 0.682, P = 0.169, P = 0.952, P = 0.084 and P = 0.222, respectively)." (PMID 26148476, 2015).
cancer (23 papers, 2015 to 2024). A tumor composed of atypical neoplastic, often pleomorphic cells that invade other tissues. "To further explore the prognostic value of RIPK4 in tumors, we performed pan-cancer assays and observed that RIPK4 expression was associated with KIRP, KIRC, PAAD, COAD, and ACC." (PMID 35310605, 2022). "Therefore, it is worthwhile to test the activity status of the different cancer-associated RIPK4 mutants." (PMID 37688617, 2023). "The pan-cancer validation results showed that RIPK4 was associated with survival in five tumors." (PMID 35310605, 2022). "Recent researches indicated that RIPK4 was associated with the progression of many cancers." (PMID 33487072, 2021). "In addition to mutations, RIPK4 is aberrantly expressed in various kinds of cancers, including skin, ovarian, cervical SCCs." (PMID 32923402, 2020). "Moreover, KEGG assays indicated that RIPK4 expression may be associated with focal adhesion, proteoglycans in cancer, central carbon metabolism in cancer, and insulin secretion." (PMID 35310605, 2022). "The connection we revealed between LPA and RIPK4 inhibition would provide insight not only on RIPK4-regulated cancer progression but also facilitate understanding other aspects of RIPK4-related biology." (PMID 38630705, 2024). "Taken together, these data implicate RIPK4 as a putative driver of TNBC progression through cancer cell-intrinsic expression of RIPK4." (PMID 38744952, 2024). "RIPK4 is a key member of the group of Receptor Interacting Proteins (RIPs) and is aberrantly expressed in multiple cancer types." (PMID 36766756, 2023). "RIPK4, receptor-interacting protein serine/threonine kinase 4, is aberrantly expressed in multiple cancer types and is a key member of the receptor-interacting protein group, which has been studied in detail in OC." (PMID 36642706, 2023). "KEGG pathway analysis displayed that the dysregulated genes in specimens with high RIPK4 expressions were enriched in focal adhesion, proteoglycans in cancer, central carbon metabolism in cancer, and insulin secretion." (PMID 35310605, 2022). "The effect of RIPK4 in apoptosis and cell cycle arrest in other types of cancer cell lines should further be explored." (PMID 35186499, 2022). "To further examine the possible abilities of RIPK4 as a potential biomarker in pan-cancer, we conducted survival assays." (PMID 35310605, 2022). "Expression level, subcellular localization, and tissue localization of RIPK4 in human cancers should be further clarified to improve our understanding of the biological bases of cancer progression." (PMID 32923402, 2020). "RIPK4 is a critical activator of NF-κB signaling, which contributes to cancer development and progression, as well as to the resistance of cancer cells to chemoradiotherapy." (PMID 32923402, 2020). "Further study of the mechanisms of RIPK4 expression in human cancers is also required to improve our understanding of the biological basis of cancer progression." (PMID 29867225, 2018). "In summary, we reported the RIPK4 expression pattern in BC and demonstrated the potential role of RIPK4 in cancer aggression." (PMID 29867225, 2018). "Aberrant expression of receptor interacting protein kinase 4 (RIPK4), a crucial regulatory protein of Wnt/β-catenin signaling, has recently been reported to be involved in several cancers." (PMID 26148476, 2015). "To gain deeper insights into how Ripk4 expression correlates with poor survival in vivo, we explored whether the expression of Ripk4 in cancer cells might facilitate extravasation to metastatic sites, such as the lungs." (PMID 38744952, 2024). "The role of RIPK4 in cancer is thus double-sided and seems to depend on the cellular context." (PMID 37688617, 2023). "Previous studies identified that RIPK4 acted as a significant oncogene in many cancers." (PMID 33487072, 2021). "Previous studies also indicated that RIPK4 acted as an oncogene in several cancers." (PMID 33487072, 2021).
cancer (continued). "Depending on the context, RIPK4 acts as a cancer “suppressor” or oncogene." (PMID 34768934, 2021). "We performed RT-qPCR (n = 40) to detect RIPK4 mRNA expression in cancer tissues and adjacent normal liver tissues in patients with HCC, and the results revealed that RIPK4 mRNA expression was significantly reduced in cancer tissues compared with adjacent tissues (p < 0.05)." (PMID 34222329, 2021). "Mounting evidence suggests that RIPK4 is aberrantly expressed in various kinds of cancers." (PMID 32923402, 2020). "The IHC results showed that the RIPK4 protein was present primarily in cytoplasm of cancer cells." (PMID 29867225, 2018). "Hence, RIPK4 may have a context-specific function in different cancer progression and signal transduction (Xu, Wei & He, 2020)." (PMID 35186499, 2022). "Moreover, some studies indicated that overexpression of RIPK4 could lead to resistance of chemotherapy and promote the progression and recurrence of cancers through activating NF-κB and Wnt/β-catenin signal pathways." (PMID 33487072, 2021). "Thus, targeting the RIPK4 pathway might represent a new therapeutic strategy to improve the therapy and survival of patients with BC or other cancers." (PMID 29867225, 2018). "Through gene profiling and targeted CRISPR screening approaches in mouse models of cancer, we identified ELOVL4, (elongation of very-long-chain fatty acid-4) as a downstream target of RIPK4." (PMID 36765696, 2023). "In CRC, its abundance is correlated with the expression of RIPK4, which regulates WNT signalling and the NF-κB pathway, and is upregulated in several cancer types, including colon cancer." (PMID 35577971, 2022). "Further studies were needed to clarify the role of RIPK4 in the prognosis of skin SCC and other different kinds of cancers." (PMID 35186499, 2022). "We explained that RIPK4 is an effective gene for inhibiting HCC metastasis and exerts a cancer suppressing effect by inhibiting the STAT3 pathway, as demonstrated by wound healing, Transwell and Western blotting experiments." (PMID 34222329, 2021). "Thus, targeting RIPK4 may be a viable approach for cancer therapy." (PMID 32923402, 2020). "The development of cancer has been the subject of extensive research, with a total of 615 papers examining the effects of RIPK1, 119 papers investigating the effects of RIPK2, 550 papers exploring the effects of RIPK3, and 54 papers analyzing the effects of RIPK4." (PMID 38164277, 2024). "Our results also confirmed that RIPK4 increased the transcription activity of β-catenin in 293T cells but not in CSCC cells, thereby indicating that the cancer-related functions of RIPK4 in CSCCs may not be explained by its regulating effects on Wnt/β-catenin signaling activity." (PMID 26148476, 2015).
epithelial carcinomas (1 paper, 2021). "In addition, previous studies have demonstrated that RIPK4 can activate the NF-κB pathway and promote malignant behaviours in epithelial carcinomas." (PMID 33855091, 2021).
metabolic disease (1 paper, 2025). A congenital disorder (due to inherited enzyme abnormality) or acquired (due to failure of a metabolically important organ) disorder resulting from an abnormal metabolic process. "Notably, these newly discovered RIPK4 variants (c.1354G > A:p.E452K; c.1558A > T:p.T520S) were not present in the Genome Aggregation Database (GnomAD) or the China Metabolic Disease Database (CMDB)." (PMID 39833848, 2025).
RIPK4 also shares sentences with these, for which no sentence is quoted: colorectal cancer (4 papers); cryptorchidism (2); gastric cancer (2); hypospadias (2); Micropenis (2); Behcet disease (1); bone metastasis (1); chordoma (1); Curly Hair-Ankyloblepharon-Nail Dysplasia Syndrome (1); Nail dysplasia (1); ovarian serous carcinoma (1); ovarian serous cystadenocarcinoma (1); pterygium (1); synovial sarcoma (1); thymoma (1); van der Woude syndrome (1); viral infection (1).